TMEM132C (transmembrane protein 132C)
Synonyms: DKFZp761O2018; PPP1R152
Tractability: Antibody: UniProt predicts a signal peptide or a membrane-spanning region; the Human Protein Atlas places it where antibodies can reach.
Gene: Protein-coding gene on chromosome 12 (128,267,170 to 128,707,911, forward strand). Ensembl gene ENSG00000181234.
Subcellular location: Membrane
Subcellular location (Human Protein Atlas): Centrosome; Cytosol; Plasma membrane
Gene Ontology:
Cellular component: membrane
Genetic constraint (gnomAD): Loss-of-function variants: 29 observed, 54.99 expected, observed/expected ratio (o/e) 0.53, 90% interval 0.39 to 0.72. The upper end of that interval is the gene's LOEUF score, 0.72, which puts it in group 2 of 6, group 1 being the genes least tolerant of losing a copy. Missense variants: 1,393 observed, 1,434.3 expected, observed/expected ratio (o/e) 0.97, 90% interval 0.93 to 1.01. Synonymous variants: 650 observed, 607.14 expected, observed/expected ratio (o/e) 1.07, 90% interval 1 to 1.14.
Homologues: Orthologues: chimpanzee TMEM132C (99% identical), macaque TMEM132C (96% identical), pig TMEM132C (85% identical), dog TMEM132C (81% identical), mouse Tmem132c (78% identical), rat Tmem132c (77% identical), guinea pig TMEM132C (71% identical), tropical clawed frog tmem132c (66% identical), zebrafish TMEM132C (51% identical), zebrafish TMEM132C (49% identical), zebrafish TMEM132C (33% identical), Drosophila melanogaster dtn (28% identical), and 1 more. Paralogues in human: TMEM132D (60% identical), TMEM132B (52% identical), TMEM132E (42% identical), TMEM132A (32% identical).
Diseases named in the same sentence as TMEM132C in open-access papers:
TMEM132C is named in the same sentence as 25 diseases in open-access papers, as found by Europe PMC text mining. Sharing a sentence is not in itself a finding about the gene and the disease. The quoted sentences say what the papers report.
breast carcinoma (6 papers, 2019 to 2023). "One report has implicated the cg04475027 methylation site on TMEM132C, as a marker for breast cancer." (PMID 33680922, 2020). "Three of these, TDRD10, PRAC2 and TMEM132C, contained CpG sites that showed diagnostic and prognostic value in breast cancer, particularly in estrogen-receptor (ER)-positive samples." (PMID 30866861, 2019). "Novel DNA methylation markers were identified, of which cg12374721 (PRAC2), cg18081940 (TDRD10) and cg04475027 (TMEM132C) show promise as diagnostic and prognostic markers in breast cancer as well as other cancer types." (PMID 30866861, 2019). "Using a genome wide approach to analyze the DNA methylation and expression patterns in breast cancer and normal breast, PRAC2, TDR10, and TMEM132C genes have been identified that can serve as novel DNA methylation-gene markers of diagnostic and prognostic significance in breast cancer." (PMID 36185256, 2022). "Genes PRAC2, TDR10 and TMEM132C showed differential methylation and differential expression in breast tumor samples relative to normal breast tissue and also contained CpG sites showing diagnostic and prognostic value in breast cancer." (PMID 30866861, 2019). "In addition to the identification of PRAC2, TDR10 and TMEM132C as novel DNA methylation-gene markers in breast cancer, analysis of their expression and diagnostic and prognostic potential revealed they may also be relevant in other cancer types." (PMID 30866861, 2019). "Expression of TMEM132C was downregulated across all 13 non-breast cancer cohorts while PRAC2 was upregulated in 77% of cohorts." (PMID 30866861, 2019). "Sites cg12374721 (PRAC2), cg18081940 (TDRD10) and cg04475027 (TMEM132C) may be effective as diagnostic and prognostic tools not only in breast cancer but also in other cancer types." (PMID 30866861, 2019). "As a result, the combined model for TN breast cancer (TMEM132D, TMEM132C, MYO15B, S) demonstrated statistical significance (p = 0.0004) vs. the epigenetic model (TMEM132D, TMEM132C, MYO15B)." (PMID 36900421, 2023). "Furthermore, 3 CpGs located in genes not previously associated with cancer, PRAC2, TDRD10 and TMEM132C, were able to predict breast cancer overall survival, and more particularly survival of ER-positive patients, suggesting their potential as diagnostic and prognostic markers in BC." (PMID 30866861, 2019). "For TN breast cancer, the inclusion of the clinical stage in the epigenetic classifier made it possible to achieve an area under the curve cvAUC = 0.87; 95% CI = 0.86–0.88 with a sensitivity of 0.71 and a specificity of 0.80 for the “TMEM132D, TMEM132C, MYO15B, S” panel." (PMID 36900421, 2023).
breast tumor (2 papers, 2019 to 2021). "TMEM132C has been reported to show differential methylation and is downregulated by DNA hypermethylation in breast tumors." (PMID 33047283, 2021). "PRAC2 is upregulated in breast tumor tissue whereas TDR10 and TMEM132C are both downregulated." (PMID 30866861, 2019). "Unlike PRAC2, genes TDRD10 and TMEM132C are both downregulated in breast tumor tissue when compared to normal tissue." (PMID 30866861, 2019).
asthma (1 paper, 2015). "We identified TMEM132C as a potential candidate gene at 12q24.3, which is a previously reported locus of asthma and spirometric indices." (PMID 26430897, 2015).
Cognitive impairment (1 paper, 2023). Abnormal cognition is characterized by deficits in thinking, reasoning, or remembering. "TMEM132C, whose levels were increased in the patient-derived cells, encodes a neural adhesion molecule associated with AD which is also independently associated with cognitive impairment in a hypotensive population and with high-altitude adaptation in Tibetans." (PMID 37566069, 2023).
congenital cataracts (1 paper, 2024). "TMEM132C has also been shown to be differentially regulated in the NPCs of another disease with congenital cataracts and intellectual disability, Lowe syndrome." (PMID 38607030, 2024).
dementia (1 paper, 2024). Loss of intellectual abilities interfering with an individual's social and occupational functions. "There are no functional annotations which elucidate how the BIN1 locus might be impacting AD through regulation or modification of TMEM132C, however, TMEM106B is a known dementia-associated gene which has functions in lysosome function and homeostasis." (PMID 38883718, 2024).
hearing loss (1 paper, 2019). "Finally, the TMEM132C (Transmembrane Protein 132C) gene belongs to a family of five TMEM132 proteins, which are associated with hearing loss, panic disorder and cancer." (PMID 30866861, 2019).
Nausea (1 paper, 2024). A sensation of unease in the stomach together with an urge to vomit. "Among the top 20 gene-annotated SNPs in the HS GWAS with regard to the association with nausea, we selected the TMEM132C rs7296262 SNP (i.e., the only SNP that was investigated in a previous study of a psychiatric disorder at the survey stage on 24 May 2024)." (PMID 39201532, 2024).
cancer (3 papers, 2017 to 2024). A tumor composed of atypical neoplastic, often pleomorphic cells that invade other tissues. "Thus PRAC2, TDR10 and TMEM132C may be more relevant in rapidly growing cancers." (PMID 30866861, 2019). "For instance, NOVA1, NRXN1, TMEM132C, USP44, VIPR2, and ZSCAN23 were consistently downregulated in nine cancers." (PMID 28060724, 2017).
nervous system disorder (1 paper, 2025). A non-neoplastic or neoplastic disorder that affects the brain, spinal cord, or peripheral nerves. "Although the exact functions of TMEM132C are still not fully understood, transmembrane proteins (TMEMs) are increasingly recognized for their roles in various nervous system disorders." (PMID 40869915, 2025).
TMEM132C also shares sentences with these, for which no sentence is quoted: tumor (3 papers); abortion (1); angiosarcoma (1); cardiovascular diseases (1); Colon Cancer (1); head and neck squamous cell carcinoma (1); Hepatic steatosis (1); Intellectual disability (1); liver cancer (1); Lowe syndrome (1); Obesity (1); panic disorder (1); psychiatric disorder (1); somatotropinoma (1); type 2 diabetes (1).